TSPO (translocator protein)
Diseases named in the same sentence as TSPO in open-access papers (continued):
Sharing a sentence is not in itself a finding about the gene and the disease.
depression (continued). "Positron emission tomography (PET) reveals increased TSPO levels in ACC in patients with moderate to severe depression, indicating microglial activation, and higher TSPO levels in patients with suicidal ideation." (PMID 40881472, 2025). "The observed decrease in TSPO and VDAC protein expression in a human cell model of depression raises intriguing possibilities regarding the role of TSPO in the pathophysiology of stress-related disorders and depression." (PMID 39684592, 2024). "Considering the modulatory function of TSPO and the similar functional phenotype of cells derived from patients with depression, we discuss a role of TSPO in the etiology or pathology of MDD." (PMID 39684592, 2024). "It is worth noting that higher in vivo TSPO levels have been previously reported in patients with active episodes of major depressive disorder." (PMID 38615126, 2024). "Though TSPO does label some sparse astrocytes and recruited monocytes, authors suggest it is likely that this increase in signal represents more microglia in depression." (PMID 38175420, 2024). "Neuroinflammation in depression is characterized by activation of microglia with increased expression of the activation marker translocator protein." (PMID 37735410, 2023). "This study’s findings suggest that the alleviation of the pain–depression comorbidity by sEH inhibitors occurs via distinct signaling pathways involving TSPO or AHR." (PMID 36732752, 2023). "The results showed that TSPO VT was significantly higher in the prefrontal cortex, ACC, and insula suggesting microglial activation, with TSPO VT in the ACC correlating with the severity of depression." (PMID 36624089, 2023). "Studies using positron emission computed tomography (PET) imaging with the 18 kDa translocator protein (TSPO) as a biomarker of microglia have shown that neuroinflammation exists in multiple brain regions in depression patients." (PMID 36624089, 2023). "The expression of TSPO increased in brain injury and neuroinflammation, and decreases in patients with anxiety, schizophrenia, and major depression." (PMID 36438847, 2022). "For example, clinical studies have shown that the total distribution of TSPO is increased in patients with depression." (PMID 35250485, 2022). "The total TSPO distribution volume appears to be elevated in the hippocampus in depression patients." (PMID 35250485, 2022). "Overall, changes in TSPO expression in hippocampal microglia were largely consistent with the microglial changes occurring during stress-induced depression." (PMID 35250485, 2022). "Minocycline, a tetracycline antibiotic capable of lowering microglial activation and TSPO volume in rodents, has also been shown to attenuate rodent behaviors indicative of depression." (PMID 33854417, 2021). "Translocator protein (TSPO)–targeted positron emission tomography (PET) has been used to assess neuroinflammation in major depressive disorder." (PMID 33515765, 2021). "On the other hand, in depression, TSPO seems to be upregulated mostly in the anterior cingulate and prefrontal cortex." (PMID 33433698, 2021). "TSPO was overall lower in depression patients receiving SSRI medication compared to unmedicated patients." (PMID 33433698, 2021). "In a similar model used in this study, the STZ/HFD in rats, the role of TSPO in the treatment of depression in T2D was evaluated by demonstrating the pharmacological effects of AC-5216, a ligand for TSPO." (PMID 32093016, 2020). "Neuroimaging and postmortem studies have shown an increase in mitochondrial translocator protein (tryptophan-rich sensory proteins -TSPO) in subjects with major depressive disorder." (PMID 32849076, 2020). "After treatment for 2 weeks, ZBD-2 alleviated depression-like behaviors and enhanced the TSPO level in a PPD animal model." (PMID 29506545, 2018). "Our present study will prompt a strong interest on both the preclinical and clinical TSPO in vivo imaging for depressive disorders." (PMID 29343269, 2018).
depression (continued). "Taking together, these demonstrate that TSPO plays a significant role in the treatment of depression in T2DM." (PMID 27886206, 2016). "Translocator protein (18kDa) (TSPO) and allopregnanolone play an important role in the depression treatment." (PMID 27886206, 2016). "Recent TSPO PET imaging studies provided accumulating in vivo evidence to support the association between brain neuroinflammation and depression." (PMID 26809249, 2016). "The present study demonstrated that the role of TSPO and allopregnanolone in the treatment of depression in T2DM." (PMID 27886206, 2016). "This study was initiated with the objective of evaluating the role of TSPO and allopregnanolone biosynthesis in the treatment of depression in T2DM." (PMID 27886206, 2016). "To date, two studies assessed TSPO in patients with major depressive disorder and one study examined bipolar I patients." (PMID 28781965, 2015). "Although the data is cross-sectional, evidence suggests that antidepressant treatment alleviates the progressive increase in TSPO-VT within the duration of untreated depression, indicating a relationship between accumulated disease burden and microglia activation." (PMID 38916735, 2024). "In addition to synergistically promoting depressive symptoms with AHR, sEH can also inhibit normal TSPO function by inducing the co-occurrence of pain and depression." (PMID 36732752, 2023). "Despite TSPO’s effect on anxiety and depression, the exact mechanism by which it acts is still unknown." (PMID 37416505, 2023). "Positron emission tomography imaging studies demonstrated the involvement of neuroinflammation in psychiatric disorders, including psychosis, depression, substance use, and obsessive-compulsive disorder, by showing elevated translocator protein (TSPO) binding in activated microglia." (PMID 36750547, 2023). "We hypothesized that if the BCSFB were indeed a mediator between peripheral and central inflammation in depression, we would observe a direct correlation between central inflammation, here marked by TSPO parenchymal expression, and CP volume." (PMID 34972034, 2022). "In our study, we did not see any elevation of CP [11C]PK11195 in depression, but we were able to replicate the association between CP volume and CP TSPO uptake as reported by in relapsing remitting multiple sclerosis patients." (PMID 34972034, 2022). "Our results revealed dynamic changes in TSPO levels and localization in microglia and astrocytes during stress, thereby providing a theoretical basis for studying glial changes during the onset of depression." (PMID 35250485, 2022). "Thus, it is necessary to explore the relationships between TSPO, microglia, and astrocytes in the context of depression." (PMID 35250485, 2022). "The findings were robust to depression severity, BMI, medication status, and other explored variables, and statistical analysis indicates that the effect was driven by significant increases of TSPO in one third of the MDD patients." (PMID 36226319, 2022). "The positive correlation between depressive episode severity and TSPO volume indicate that microglia activation and neuroinflammation may contribute to depression severity." (PMID 33854417, 2021). "Therefore, in our present study, we first utilized the [18F] DPA-714, the PET ligand which binds to active-stage TSPO that is upregulated on microglia, to demonstrate neuro-inflammation imaging in rat models of depression." (PMID 29343269, 2018). "There is also a need to study inflammatory markers in CSF and—as central inflammation can be assessed using positron emission tomography (PET) ligands specific for the translocator protein (TPSO)—to undertake in vivo PET studies both during depression and after recovery." (PMID 27918465, 2016). "The findings advance our knowledge that TSPO selective ligands may be a promising new pharmacological class of drugs for the future treatment of depression in T2DM." (PMID 27886206, 2016).
depression (continued). "To further evaluate the role of TSPO in the treatment of depression in T2DM, we determined whether pharmacological effects of AC-5216 were antagonized by PK11195 (TSPO antagonist) in HFD-STZ rats." (PMID 27886206, 2016). "This study indicates that the antidepressant-like effects of AC-5216 on HFD-STZ rats, suggesting that TSPO may represent a novel therapeutic target for depression in T2DM." (PMID 27886206, 2016). "However, few studies have evaluated TSPO and allopregnanolone in the treatment of depression in T2DM." (PMID 27886206, 2016). "Further studies should be conducted to investigate the putative mechanisms of the interaction on depression in T2DM (e.g allopregnanolone biosynthesis, GABA system), as well as the role of TSPO in the modulation of T2DM aiming at new strategies to treat depression in patients with T2DM." (PMID 27886206, 2016). "During recent years, a series of positron emission tomography (PET) studies have been published using radioligands for the translocator protein (TSPO) to study microglia activation in schizophrenia, bipolar I disorder, major depression, autism spectrum disorder, and drug abuse." (PMID 28781965, 2015). "The role of neuroinflammation in brain tumor-associated depression depression could also be further studied by molecular imaging approaches targeting activated microglia, e.g., by using PET radioligands for the translocator protein." (PMID 26475140, 2015). "Alternatively, the measurements of TNFα concentrations and parenchymal TSPO expression may not provide a comprehensive representation of peripheral or central immune activity associated with depression." (PMID 39657983, 2025). "In addition, the dynamic monitoring of TSPO levels in vivo could help elucidate how TSPO, microglia, and astrocytes interact during the pathogenesis of depression." (PMID 35250485, 2022). "It is still a matter of debate whether an increased TSPO ligand binding in depression is due to the proliferation of microglial cells or infiltration of circulating macrophages, which also express high amounts of TSPO protein through the blood-brain-barrier (BBB)." (PMID 31075818, 2019). "However, little is known about the importance of TSPO in the treatment of depression in T2DM." (PMID 27886206, 2016). "Then, the possibility of generalizing the model to different TSPO tracers was evaluated on [18F]DPA-714 and [11C]-(R)-PK11195 PET scans on healthy volunteers, individuals with mild cognitive impairment 45, and depressive disorder patients." (PMID 39975931, 2025). "We also observed a reduced TSPO and VDAC expression in cells derived from patients suffering from major depressive disorder (MDD)." (PMID 39684592, 2024). "sEH underlies the mechanisms of the comorbidity of chronic pain and depression and that TPPU exerts a beneficial effect on anhedonia behaviors in a pain model via AHR and TSPO signaling." (PMID 36732752, 2023). "Our results motivate the use of TSPO PET in clinical and preclinical research for identifying the optimal treatment window and developing treatment plans for depression." (PMID 35250485, 2022). "The observed temporospatial neuroinflammation-related TSPO-PET imaging data generated herein coincide well with data from prior IHC-based analyses of inflammation-induced and stress-related depression models." (PMID 35113011, 2022). "In particular, a number of studies have revealed a strong relationship between a high mental illness score and increased expression of translocator protein (TSPO, a marker of microglial-derived neuroinflammation) in patients with depressive disorders." (PMID 36052132, 2022). "Others have also focused on the translocator protein (18kDa) (TSPO) which is key for neurosteroidogenesis or a novel, synthetic, neuroactive steroid SGE-516 to improve postpartal depression-like symptoms in mice." (PMID 33585496, 2020). "However, the importance of TSPO in the remedy of depression in T2DM is still unknown." (PMID 27886206, 2016).
depression (continued). "This study highlights the value of TSPO PET imaging for monitoring dynamic glial changes during therapeutic intervention and provides supportive evidence for targeting neuroimmune pathways in depression." (PMID 41751234, 2026). "Mostly using PET-ligands for Translocator Protein (TSPO) that tracks monocyte-lineage cells, researchers have shown that there is increased signal for those with depression in specific limbic areas, including the anterior cingulate cortex, hippocampus, insula, prefrontal cortex, and temporal cortex." (PMID 38175420, 2024). "Several translocator protein (TSPO) binding positron emission tomography (PET) studies demonstrated enhanced microglial activation in prefrontal cortex (PFC), ACC and insula of patients with major depressive disorder (MDD)." (PMID 37794488, 2023). "Similarly, we saw pronounced increases in TSPO-PET signals in the prefrontal cortex, which is also known as a region showing functional and structural changes in depressions." (PMID 36226319, 2022). "Thus, the broad aim of this study was to dynamically evaluate hippocampal TSPO expression, the number of hippocampal microglia and astrocytes, and the TSPO expression in glial cells in a CUS-induced mouse model of depression." (PMID 35250485, 2022). "Here, we collected clinical questionnaire data, TSPO PET brain scans, and peripheral blood immune markers from 51 depressed subjects and 25 HCs to better establish the relationship between peripheral and central inflammation in depression." (PMID 33515765, 2021). "The data indicated that TSPO is a potential treatment target for depression in T2DM without affecting locomotor activity." (PMID 27886206, 2016). "The alternation of TSPO expression (or function) is a promising therapeutic target for depression without benzodiazepine-like side effects." (PMID 27886206, 2016). "Moreover, TSPO expression is lower in MDD patients receiving antidepressant medication than in unmedicated patients, and TSPO binding is greater in patients with chronologically advanced MDD and a long duration of untreated depression." (PMID 39684592, 2024). "While the present results may present microglia as a therapeutic target, a treatment trial with minocycline failed to rectify the elevated TSPO-PET binding in a cohort of patients with treatment-resistant depression." (PMID 36226319, 2022). "Understanding the cellular localization of TSPO in different glial cells in non-inflammatory diseases such as depression could be clinically useful." (PMID 35250485, 2022). "Therefore, we speculate that the changes in TSPO signals and the number of microglia in the CA1 region are likely to be early indicators of depression." (PMID 35250485, 2022).
schizophrenia (60 papers, 2015 to 2025). A major psychotic disorder characterized by abnormalities in the perception or expression of reality. "As expected from previous evidence 41, a widespread increase in TSPO density was reported in the whole cortex when comparing ultra-high risk of psychosis and schizophrenia patients to healthy controls." (PMID 39975931, 2025). "In conclusion, we observed significant differences in the association between neuroticism and TSPO VT when comparing HVs with those on the schizophrenia spectrum." (PMID 33354652, 2020). "Finally, endothelial cells have been shown to be involved in TSPO modulation in a model of acute inflammation induced by an adeno-associated virus encoding the tumor necrosis factor gene or in schizophrenia." (PMID 37408083, 2023). "In [11C]-PBR28 PET studies, TSPO increased in both schizophrenia and high-risk groups." (PMID 36873215, 2023). "However, PET studies conducted with different TSPO radioligands have yielded different results for patients with schizophrenia and individuals at high risk of psychosis." (PMID 37429882, 2023). "Besides, TSPO was negatively correlated with cortical volume, while cortical volume loss was observed in schizophrenia." (PMID 36873215, 2023). "However, a recent meta-analysis of five studies (75 patients and 77 healthy controls) that considered the TSPO polymorphism shows a decrease in TSPO in schizophrenia." (PMID 32839410, 2020). "Thus, the potential negative contribution of astroglial loss or vascular endotheliopathy to TSPO expression in a subset of individuals with recent-onset schizophrenia cannot be totally excluded." (PMID 28588507, 2017). "Furthermore, the research points to the need for deeper investigation into the relationship between dopamine and microglial activation in schizophrenia, suggesting that future studies should measure both TSPO and dopamine release to clarify the causal and region-specific link between them." (PMID 38673018, 2024). "The two longitudinal studies in this systematic review suggest different TSPO expression in schizophrenia, and another study found correlation between symptom severity and TSPO expression in UHR subjects." (PMID 39576337, 2025). "Our findings extend these prior findings and other evidence for glial cell abnormalities in schizophrenia to show that the inter-regional similarity of TSPO measures also differentiates people with schizophrenia from controls." (PMID 41282214, 2025). "In contrast, using PET studies for TSPO as a marker for microglial activity revealed a significant increase in the marker in schizophrenia patients with antipsychotic treatment." (PMID 40171306, 2025). "In schizophrenia patients, a moderate increase in TSPO tracer binding in whole brain gray matter was found when compared to controls when BPND was used as an outcome measure, but not when VT was used." (PMID 37016791, 2023). "A recent meta-analysis reported on the findings of 12 PET imaging studies in schizophrenia (190 schizophrenia patients and 200 healthy controls), using TSPO as a marker of neuroinflammation." (PMID 37016791, 2023). "Studies using TSPO PET imaging and synaptic markers in preclinical models of schizophrenia risk factors would be useful to further test these links, whilst the development of new tools to image glia is needed to provide greater sensitivity and specificity." (PMID 37041418, 2023). "A study showed TSPO decreased in the first-episode untreated schizophrenia compared with medicated groups." (PMID 36873215, 2023). "A meta-analysis suggested that TSPO in frontal cortex, hippocampus and temporal cortex were reduced in schizophrenia." (PMID 36873215, 2023). "Studies including patients with chronic schizophrenia, that are usually under antipsychotic treatment, report increases or normal levels of TSPO." (PMID 36443303, 2022).